EGFR (epidermal growth factor receptor)
Diseases named in the same sentence as EGFR in open-access papers (continued):
Sharing a sentence is not in itself a finding about the gene and the disease.
lung cancer (continued). "A functional network and cooperative interplay have been suggested involving nAChRs, β-AR, EGFR, and IGFR, all known to be expressed, and frequently found to co-exist in human lung cancer cells, likely leading to increased mitogenic effects enhancing oncogenesis." (PMID 36361620, 2022). "Case reports of lung cancer patients with EGFR/CTNNB1 comutations are rare, and TKIs are not considered to be effective." (PMID 36519636, 2022). "In contrast, LEPRE1 knockdown induced EGFR/Src/ERK/cofilin cascade signaling and promoted epithelial-to-mesenchymal transition (EMT), leading to pelitinib resistance in the AML cell line THP-1 and lung cancer-derived A549 cells." (PMID 35190588, 2022). "Not only EGFR facilitates proliferative signaling through downstream signaling pathways, i.e. PI3K/AKT/mTOR and RAS/ERK, EGFR signaling pathway is one of the activated pathways in lung cancer and employs downstream RAS or ERK pathways to direct proliferative signaling for lung cancer cells." (PMID 34635059, 2021). "The changes in the down-stream signaling pathways of EGFR in lung cancer cells with and without ANXA1 knockdown or Osimertinib treatment were then studied." (PMID 34439260, 2021). "We also observed a strong negative correlation between PLK1 and FGFR3 in EGFR‐mutant lung cancer cohort, whereas there are no such correlations in BRAF‐mutant lung cancer." (PMID 34369083, 2021). "EGFR and ALK alternations often contribute to human malignancies, including lung cancer." (PMID 34654390, 2021). "TNF may also play an important role in mediating resistance to targeted inhibition, particularly in the context of EGFR inhibition in GBM and lung cancer." (PMID 33373873, 2021). "EGFR-related lung cancer is more frequent in women, non-smokers and patients of East Asian descent and is found in 15% of patients with adenocarcinoma in North America." (PMID 33652831, 2021). "Epidermal growth factor receptor (EGFR) inhibitors, for instance, are not equally effective across EGFR mutant lung cancer patients, and in almost all cases, tumors eventually acquire resistance and recur." (PMID 34061819, 2021). "But EGFR-resistance and downstream signaling gene STAT3 activation contributes to cell proliferation, anti-apoptosis, and resistance to CD8+ T cells in EGFR-positive lung cancer." (PMID 34685495, 2021). "In this work, to investigate the structure of the EGFR/RAS/RIT1 signaling network and identify therapeutic targets in lung cancer, we perform genome-wide CRISPR screens in isogenic PC9 cells where drug resistance is potently conferred by each expressed oncogene." (PMID 34373451, 2021). "Consequently, EGFR expression in pleural microvessels implies the angiogenic activity of MAPF and an unfavorable prognosis for patients with lung cancer." (PMID 34680445, 2021). "In another report, the gene fusions of six never-smoking female patients with lung cancer were analyzed by RNA-Seq; these patients had no mutations in KRAS or EGFR and were negative for EML4-ALK." (PMID 33809651, 2021). "The exosomes secreted by lung cancer cells that enrich various proteins, such as EGFR, KRAS, claudins, and RAB-family proteins that promote the development of lung cancer, can be effective biomarkers for the early diagnosis of lung cancer and the basis of targeted therapy." (PMID 34769444, 2021). "Due to this, there remains a reliance on chemotherapy; in contrast, in paradigms like epidermal growth factor receptor (EGFR)-mutant lung cancer and anaplastic lymphoma kinase (ALK)-translocated lung cancer, effective targeted therapy has mitigated the need of chemotherapy." (PMID 33589591, 2021).
lung cancer (continued). "Epidermal growth factor receptor (EGFR) is a type of receptor in the human body that interferes with the maintenance and growth of epithelial tissues, and the irregular expression of EGFR is related to the occurrence of lung cancer." (PMID 34577205, 2021). "Activating EGFR mutations in ADC are most common among non-smokers, and younger, female, Asian lung cancer patients." (PMID 33869038, 2021). "Its prognostic impact in lung cancer and connection between EGFR-targeted therapy and DR4 modulation has not been reported and thus was the focus of this study." (PMID 33664875, 2021). "To investigate fusion genes in lung cancer, we analysed RNA-sequencing data of 29 patients with lung adenocarcinoma (NCCLUAD) who lacked activating mutations in KRAS or EGFR." (PMID 33204025, 2021). "As for lung cancer, the BTK inhibitor ibrutinib effectively suppresses the proliferation of certain EGFR mutant lung cancer cells through the inhibition of the autophosphorylation of EGFR." (PMID 34315851, 2021). "Mesenchymal characteristics were observed in vitro and in vivo EGFR-mutant lung cancer models that acquired resistance to first-generation EGFR-TKI with no genetic alterations." (PMID 33170304, 2021). "Still, little is known about the relationship between EGFR and HDAC1, specifically in lung cancer." (PMID 33976119, 2021). "Among cell lines available in our lab, we found that human EGFR was highly abundant in lung cancer H358 and HCC827 cells, but negative in leukaemia MOLM13 and neuroblastoma N2A cells." (PMID 33643546, 2021). "Our results show that CDK9 inhibition significantly reduces the viability of K-Ras mutant (A549, H460, H23) and EGFR mutant (H1650, H1975, PC9) lung cancer cell lines at very low nanomolar to less than 0.5 μM concentration of CDK9 inhibitors, namely, AZD4573, LY2857785, and SNS032, respectively." (PMID 34359807, 2021). "A high EGF amount plus EGFR overexpression in lung cancer cells, create conditions for the growth of some EGF-dependent tumors, even in the absence of specific EGFR driver mutations." (PMID 34211836, 2021). "Therefore, we conclude that, in response to EGFR activation, PSAT1 contributes to lung cancer cell migration, in part, by promoting nuclear PKM2 translocation." (PMID 34439090, 2021). "In addition to lung cancer, our laboratory also demonstrated the function of DHHC20 in breast cancer cell line MDA-MB-231 which has elevated levels of wild-type EGFR." (PMID 34610265, 2021). "In our cohort, higher CD8+ TILs level in brain tumor had a prolonged OS for either EGFR-mutant LUADs who receiving TKI treatments or patients with lung cancer who not receiving TKI treatments, indicating CD8+ TILs level as a robust prognostic factor." (PMID 33479213, 2021). "All of the clinically-relevant variants of the EGFR, ALK, BRAF and KRAS genes are unambiguously lung cancer-associated and do not meet CHIP criteria; therefore, the presence of CHIP-associated variants doesn’t affect clinical decision making." (PMID 34031447, 2021). "First, all lung cancer cell lines did not exhibit a metabolic shift from glycolysis to mitochondrial OXPHOS under long-term exposure to EGFR-TKIs." (PMID 34367462, 2021). "Gene 33 may also contribute to resistance of lung cancer stem cells to the EGFR TKI by suppressing their transition from self-renewal to malignant differentiation, a process dependent on EGFR signaling." (PMID 34206547, 2021). "Notably, previous studies reported that EGCG inhibits the activation of EGFR and human epidermal growth factor receptor 2 (HER2) in human lung cancer cells, and EGCG inhibits the tyrosine kinase activity of EGFR in human A431 epidermoid carcinoma cells." (PMID 34299635, 2021). "To characterize whether EGFR-overexpressed or mutated carcinoma cells are sensitive to cinobufagin, we screened more cancer cell lines, including glioblastoma, lung cancer, colorectal cancer (CRC), and liver cancer cell lines, with different status of EGFR." (PMID 34925034, 2021).
lung cancer (continued). "However, moderate response and development of acquired resistance upon EGFR TKI therapy limits the clinical benefit and contributes to the incredibly low survival rates among lung cancer patients." (PMID 34359849, 2021). "Hence, downregulation of MAPK signaling by anti-EGFR antibodies, or inhibitors of EGFR, MEK, and BRAF enhances the expression of HLA-I in several types of tumors, such as lung cancer, melanoma, and head and neck squamous cell cancer." (PMID 34458148, 2021). "Exosomes expressing epidermal growth factor receptor (EGFR) expression can stimulate tolerogenic dendritic cells and tumor-specific regulatory T cells (Tregs) that attenuate the role of anti-tumor CD8-positive T cells and promote lung cancer growth." (PMID 34572829, 2021). "Finally, we identified a potential combination of EGFR and MEK-targeted therapies as a possible treatment option for patients with EGFR-driven lung cancer with NRAS gene amplification as a bypass signaling pathway." (PMID 34642436, 2021). "Patient characteristics were in line with typical patients with newly diagnosed EGFR-mutant lung cancers (predominantly never/light smokers, women)." (PMID 34140482, 2021). "Likewise, LncRNA SOX2‐OT promotes a functional modulation of the EGFR‐AKT‐ERK expression‐activation, promoting resistance to cisplatin/EGFR‐TKI‐erlotinib therapy, determining poorer overall survival of lung cancer patients." (PMID 33433063, 2021). "EGFR gene mutations are seen in up to 40% of never smoker, compared to 1% in the smoker, while KRAS mutation is almost exclusively limited to smoker’s lung cancer." (PMID 34181354, 2021). "The results showed that Wogonin may act on lung cancer through inhibition of EGFR tyrosine kinase by the PI3K-Akt signaling pathway and the ERBB signaling pathway." (PMID 34630106, 2021). "In summary, antiproliferative activity of SLURP-1 in lung cancer cells is mainly mediated by interaction with α7-nAChR, which is realized by means of loop I. However, other molecular targets, e.g., EGFR and PDGFR, are involved in control of lung cancer cell migration by SLURP-1." (PMID 34595181, 2021). "In contrast with other tumors such as lung cancer, in PDAC, activating mutations in EGFR have never been found." (PMID 34440587, 2021). "We found that higher TCR clonality of BM in EGFR-mutant LUADs who receiving TKI treatments but lower TCR clonality in patients with lung cancer who not receiving TKI treatments had a prolonged OS since brain tumor resection." (PMID 33479213, 2021). "The history of research and development of EGFR-TKI and ALK inhibitors in lung cancer treatment reveals that finding clear driver genes for tumors is of great significance for developing new drugs, selecting the right treatment population and ensuring the therapeutic efficacy of targeted drugs." (PMID 34168983, 2021). "In addition, we identify many other candidate EGFR-, KRAS-, and RIT1 dependencies that should be further explored as drug targets for lung cancer therapy." (PMID 34373451, 2021). "The finding that the loss of DHHC20 and EGFR palmitoylation in MDA-MB-231 breast cancer cells and SW1573 lung cancer cells extended the duration of EGFR signalling in response to EGF highlights a possible connection between EGFR palmitoylation and EGFR signalling kinetics." (PMID 34610265, 2021). "In addition, it has also been shown that overexpression of IGF2 induces resistance to targeting agents, such as the EGFR inhibitors, osimertinib and erlotinib, by re-activating the AKT and MAPK pathways in lung cancer and cholangiocarcinoma." (PMID 34067117, 2021). "EGFR plays an important role in lung carcinogenesis, while its expression level is independent of EGFR positivity rate, lung cancer stage, lung cancer differentiation, the presence of lymph node metastasis, and so on." (PMID 34178945, 2021).
lung cancer (continued). "This study provides evidence of the mechanism involving EGFR in the anticancer effect of SH003 with DTX, and may herald new therapeutic methods using herbal medicine for lung cancer." (PMID 34445110, 2021). "In view of the critical role of EGFR and STK11 mutations in the efficacy of lung cancer treatment, we analyzed the differences of BMP5 mRNA expression in patients with and without EGFR and STK11 mutations." (PMID 34745928, 2021). "LCCDEs EGFR induce tolerogenic dendritic cells and tumor antigen-specific regulatory T cells (Treg) to inhibit anti-tumor function of CD8+ T cells and thus promote lung cancer growth." (PMID 33504342, 2021). "Unlike lung cancer, gliomas contain a wide variety of EGFR alterations, which make it difficult to target." (PMID 35601813, 2021). "EGFR, as a receptor, acts as signal transduction for the PI3K/Akt and MAPK pathways in lung cancer." (PMID 34067437, 2021). "Finally, we detail the current landscape of additional actionable alterations (EGFR, ALK, ROS1, MET) in lung cancer, a biomarker-rich malignancy that has greatly benefitted from the precision oncology revolution." (PMID 34198738, 2021). "The expression of exosomal miR‐260 was obviously downregulated in the medium of lung cancer cell lines with mutant EGFR, with no significantly changes occurring in the EGFR wild‐type cell lines." (PMID 33682961, 2021). "Typically, other driver mutations (e.g., EGFR, ALK, and ROS) of lung cancer tend to occur in never-smokers." (PMID 34205733, 2021). "Finally, two pathways for EGFR protein degradation modulated the stability of EGFR and inhibited the EGFR/Ras/MER/ERK signal pathway, leading to reduced proliferation of lung cancer cells." (PMID 33391419, 2021). "Recent studies showed that combination of EGFR tyrosine kinase inhibitor and AKT inhibitors could be a rational therapeutic approach for lung cancer patients." (PMID 33430939, 2021). "We hypothesized that there are inherent differences in immunopeptide processing and presentation between EGFR TKI-sensitive and -resistant EGFR mutant lung cancer." (PMID 34638461, 2021). "For example, in colorectal cancer, coexistant K-Ras and PI3K mutations decrease sensitivity to PI3K and mTOR inhibition, and in lung cancer, the addition of a constitutively active PI3K mutant to epidermal growth factor receptor (EGFR) mutant tumors confers gefitinib resistance in vitro." (PMID 34356110, 2021). "Moreover, knockdown RhoV promoted the sensitivity of EGFR-TKI in the gefitinib resistant PC9 cells (PC9-GR) and aggravated gefitinib-induced lung cancer cell apoptosis both in PC9 and PC9-GR cells." (PMID 33767988, 2021). "Moreover, ZNRF1-mediated EGFR degradation was also observed in HeLa cervical cancer cells, indicating that ZNRF1 involvement in EGFR degradation is not limited to lung cancer cells." (PMID 33996800, 2021). "Afatinib is an approved treatment for EGFR-positive lung cancers, but it is not yet approved for the treatment of CRC." (PMID 34766923, 2021). "The lncRNAs H19 and HOTAIR have been found to be highly expressed in EGFR-TKI-sensitive lung cancer tissues, but not expressed in resistant samples." (PMID 34692550, 2021). "Combined treatment of EGFR-TKI and a YAP inhibitor prolonged survival among lung cancer patients." (PMID 33562150, 2021). "Osimertinib exerted growth inhibitory effects on the EGFR mutation-positive lung carcinoma cell lines PC9 and H1975, even with the knockdown of EGFR, and on the EGFR mutation-negative lung carcinoma cell lines A549 and LK2 at high concentrations." (PMID 34445227, 2021).
lung cancer (continued). "Radiosensitiziation could also be induced in a lung cancer model by vandetanib, an inhibitor of VEGFR2 and EGFR but also of RET and other receptors." (PMID 32903756, 2020). "Moreover, we found that higher DHPS expression correlated with higher cellular resistance to inhibitors of EGFR pathway, such as several EGFR and MEK1/2 inhibitors, in lung cancer cell lines." (PMID 32989218, 2020). "Immunotherapy targeting programmed cell death receptor 1/ligand 1 (PD‐1/PD‐L1) has been shown to exhibit good effect and durable response in epidermal growth factor receptor (EGFR) and anaplastic lymphoma kinase (ALK) wild‐type non‐small cell lung cancer (NSCLC) patients." (PMID 32500560, 2020). "As EGFR has emerged as an attractive target for anti-lung cancer drug research, its ligand or antibody has been extensively employed in capping moiety for the active targeting of MSN in lung cancer cells." (PMID 32521802, 2020). "OSI initially gained FDA approval for patients with metastatic EGFR T790M-mutant NSCLC that had progressed on first- or second-generation EGFR TKIs and has subsequently achieved approval as a first-line treatment of EGFR-mutant lung cancer." (PMID 33008019, 2020). "In summary, these in vitro and in vivo studies uncover a novel mechanism through which DRAM1 suppresses oncogenic properties of NSCLC by regulating EGFR trafficking and degradation and highlights the potential value of DRAM1 as a prognostic biomarker in lung cancers." (PMID 32943616, 2020). "Furthermore, we studied the antitumor effect of the combination of LINC00152 knockdown and EGFR inhibition and found that LINC00152 and EGFR had synergetic effects for lung cancer treatment." (PMID 32774169, 2020). "The responses of lung cancers with podoplanin-positive CAFs to EGFR tyrosine kinase inhibitors (TKIs) are worse than those of lung cancers with podoplanin-negative CAFs." (PMID 32171304, 2020). "EGFR-TKIs could increase cytotoxic CD8+ T cells and dendritic cells in the tumor environment of lung cancer." (PMID 32206449, 2020). "Activating EGFR mutations are found in about 15% of NSCLC, while ALK and ROS1 alterations are quite rare ( < 5% of lung cancers) but are frequent among light to never smokers." (PMID 32604993, 2020). "TNF, EGFR, MYC, IL-6, and JUN were identified as major hub genes of HCT on lung cancer." (PMID 32595734, 2020). "This gene rearrangement is largely independent of EGFR alterations and has been described as an actionable oncogene with incidence in 1–7% of lung cancer patients." (PMID 32549358, 2020). "Sections of lung cancer tissues were stained with specific DRAM1 and EGFR antibodies to verify the correlation between DRAM1 and EGFR, and specimens with high DRAM1 staining were negatively correlated with EGFR staining." (PMID 32943616, 2020). "All 11 patients had received systemic therapy for lung cancer before the diagnosis of LM with bloomy rind sign: 9 with an EGFR-TKI, one with an EGFR-TKI plus an anti-angiogenic antibody, and another with cytotoxic anti-cancer drugs plus an anti-angiogenic antibody." (PMID 33228799, 2020). "In patients with lung cancer on anti-EGFR, regression between H2RA and HR for OS was not significant, so the contribution of H2RA does not seem relevant for the final outcome." (PMID 32325628, 2020). "NSCLC accounts for 75–80% of total lung cancers, and more than 60% of NSCLC expresses EGFR." (PMID 32655564, 2020). "We found both protein and mRNA expression level of ERCC1 in EGFR exon 19 deletion lung cancer cell line (PC9) were lower than EGFR wild‐type cancer cell lines and noncancerous human bronchial epithelial cell lines." (PMID 31875360, 2020). "Such functions could be regulated by GPRC5A phosphorylation, since crosstalk of this receptor with EGFR induces GPRC5A phosphorylation and switch from tumor‐suppressive to oncogenic activities in lung cancer." (PMID 32115889, 2020).